NPIPB9 (nuclear pore complex interacting protein family member B9)
Tractability: No criterion of Open Targets' tractability assessment is met for any kind of drug.
Gene: Protein-coding gene on chromosome 16 (28,751,787 to 28,772,864, forward strand). Ensembl gene ENSG00000196993.
Subcellular location (Human Protein Atlas): Nucleoplasm
Genetic constraint (gnomAD): Missense variants: 2 observed, 4.12 expected, observed/expected ratio (o/e) 0.49, 90% interval 0.2 to 1.46. Synonymous variants: 2 observed, 1.26 expected, observed/expected ratio (o/e) 1.58, 90% interval 0.47 to 1.93.
Homologues: Paralogues in human: NPIPB8 (99% identical), NPIPB6 (94% identical), NPIPB7 (92% identical), NPIPB15 (88% identical), NPIPB13 (76% identical), NPIPB5 (76% identical), NPIPB12 (76% identical), NPIPB11 (76% identical), NPIPB4 (76% identical), NPIPB2 (62% identical), NPIPA3 (59% identical), NPIPA2 (59% identical), and 7 more.
Diseases named in the same sentence as NPIPB9 in open-access papers:
NPIPB9 is named in the same sentence as 1 disease in open-access papers, as found by Europe PMC text mining. Sharing a sentence is not in itself a finding about the gene and the disease. The quoted sentences say what the papers report.
Crohn disease (1 paper, 2023). A gastrointestinal disorder characterized by chronic inflammation involving all layers of the intestinal wall, noncaseating granulomas affecting the intestinal wall and regional lymph nodes, and transmural fibrosis. "Interestingly, we also found response 3′aQTLs for genes like NPIPB9, which only strongly colocalized with Crohn’s disease under IAV stimulation conditions." (PMID 38102153, 2023).